TNF (tumor necrosis factor)
Diseases named in the same sentence as TNF in open-access papers (continued):
Sharing a sentence is not in itself a finding about the gene and the disease.
infection (continued). "As seen with the Ag-specific cytokine responses, antibody responses following secondary infection between the different groups of mice followed a similar trend, albeit at much higher levels, to that observed following primary infection, with no significant reduction in the absence of TNF-α." (PMID 23483844, 2013). "Cord TNF-α levels did not predict parasite densities during subsequent infections." (PMID 24130857, 2013). "The answer to why we see an increase in TNF-α in Lum−/− corneas at the later stages of infection with live bacteria may not be a simple one." (PMID 23358433, 2013). "To verify that C6 and K7 impaired IFN-β, TNF-α, MIP-1α and IFN-β-dependent gene expression in innate immune cells, we infected human moDCs with 1 PFU/cell of MVA-WT, MVA-B, MVA-B ΔC6L and MVA-B ΔC6L/K7R and measured IFN-β, TNF-α, MIP-1α, IFIT1 and IFIT2 mRNA levels 6 h post-infection." (PMID 23826170, 2013). "However, TNF mRNA induction was systematically weakly or unaffected by GSK3 inhibitor treatment, demonstrating some differences in regulation of MDM compared to epithelial cells at 4 hours post-infection." (PMID 23785285, 2013). "In addition, in both mouse strains at weeks 2 and 8 after infection TNF-α depletion did not result in significant increases in pulmonary fungal burdens." (PMID 23936574, 2013). "In particular, interferons (IFNs), tumor necrosis factor (TNF), and toll-like receptor (TLR) ligands, among others, have been shown to stimulate the proliferation, differentiation, and repopulating ability of HSCs in multiple mouse models of infection and inflammation." (PMID 23882270, 2013). "In this study, the lack of TNF-α, IL-6 and IL-12 induction on day 10 post-infection could result in an incomplete immune response against B. pseudomallei." (PMID 23951382, 2013). "Regarding the expression of the pro-inflammatory cytokine TNF, non-immunized mice only revealed a significant increase by day 52 post-infection, while BCG-immunized mice showed high mRNA levels of TNF at earlier time points that were maintained throughout the experimental period." (PMID 22413022, 2012). "At the early steps of infection, innate cellular microbicidal mechanisms may include the production of reactive nitrogen intermediates (RNI), reactive oxygen intermediates (ROI) and cytokines (IL-12, TNF-α and IFN-γ)." (PMID 22389743, 2012). "At three and five days post-infection, ABPS pretreated mice developed stronger Th1 immune responses against malaria infection with the number of F4/80+CD36+ macrophages and levels of IFN-γ, TNF-α and nitric oxide being significantly higher than in the control group." (PMID 22348301, 2012). "Furthermore, NMII infection increased TNF-α production and neutralization of TNF-α in NMII infected cells partially blocked PARP cleavage, suggesting TNF-α may play a role in the upstream signaling involved in NMII induced apoptosis." (PMID 22303462, 2012). "Alternatively, although the cytotoxicity of the sigE mutant is reduced, it may still be sufficient to establish lethal infections in the absence of TLR4 or TNF-α." (PMID 22897969, 2012). "WNV also induces a dramatic increase in several pro-inflammatory cytokines such as tumor necrosis factor alpha (TNF-α) and interleukin (IL)-1β and -6 and chemokines such as MCP-1 and IP-10, which regulate leukocyte trafficking into the brain, and neuronal death after infection." (PMID 22953001, 2012). "Similarly, in vivo infection with IAV resulted in higher levels of primarily neutrophil attracting chemokines such as KC and MIP-2 and several proinflammatory cytokines such as IL-6, TNF and IL-1β in the lungs of A20myel-KO mice compared to wild type mice." (PMID 22396652, 2012). "To explore this possibility and to test whether IE1 alone is capable of moderating TNFα gene expression independent of the infection process, we next used transient transfection assays." (PMID 22952450, 2012).
infection (continued). "Furthermore, the increase in mortality upon blocking TNF in the early phase of TB infection was more pronounced for NFATp−/− mice, consistent with a protective effect of NFATp-dependent genes, particularly IFN-γ, in the host response to infection." (PMID 22844476, 2012). "Strikingly, IL-6, IL-1β, IL-1α, IL-10, MIP-1α, and KC (data not shown) were secreted at significantly higher levels in response to infection with C. caviae compared to C. muridarum, whereas G-CSF (data not shown), GM-CSF (data not shown), and TNF-α levels were similar between the strains." (PMID 22292031, 2012). "TNFα levels, relative to the amount of detected virus, in selected organs were significantly higher in animals infected with MCMVdie1 than in animals infected with MCMV or MCMVrev, and this was consistently observed in several genetic backgrounds and in different infection models." (PMID 22952450, 2012). "Therefore, TNF-α is believed to enhance an ongoing immune response, either Th1 or Th2, during infection but is not essential for the development of immunity." (PMID 23053395, 2012). "Moreover, infection of these cells with other RNA viruses does not significantly affect production of cytokines such as TNFα and interleukins." (PMID 22655077, 2012). "In contrast to ex-vivo stimulation of human tonsil cells and in contrast to previous studies using GAS-M89, expression of functional SMEZ during intramuscular infection of HLA-DQ8 transgenic mice did not increase local tissue levels of TNFα, IL-10, IL-17 or IFNγ." (PMID 23049698, 2012). "Inflammatory cytokines such as tumor necrosis factor α (TNFα) are released in response to infection and may have negative effects on embryo development." (PMID 22958469, 2012). "We next asked whether the absence of IE1 in the context of an infection of BMMΦ also has an effect on TNFα expression at the RNA level." (PMID 22952450, 2012). "Furthermore, peak plasma levels of TNF-α do not decrease with repeat P. falciparum infections while those of IFN-γ decline with repeated infection." (PMID 22745697, 2012). "However, in vivo infection studies show that genetic ablation of TNFα or TNFRp55 receptor is not sufficient to rescue the restricted replication phenotype of the ie1 mutant virus." (PMID 22952450, 2012). "The reason for discrepancy between mRNA and protein expression of TNF-α is not known, but we could speculate that there is posttrancriptional regulation or that protein is accumulated at the site of infection, since there is no signaling through TNFR1." (PMID 22203861, 2012). "Interestingly, the proinflammatory response of supernatants from HIV-1-infected macrophages on day 16 after infection showed marked increases in CXCL10, MCP-1, and TNF-α by Bioplex array, while other cytokines and chemokines were not significantly changed (data not shown)." (PMID 23078780, 2012). "The cellularity in the BAL fluid was significantly higher in TNF−/− mice compared to WT mice, whereas Tm-TNF mice had a number of cells comparable to WT mice at day 77 post-infection confirming that the control of inflammation during early infection was membrane TNF dependent." (PMID 22132068, 2011). "However, final B cell maturation is abrogated by infection-induced apoptosis of transitional B cells of both the T1 and T2 populations which is not uniquely dependent on TNF-, Fas-, or prostaglandin-dependent death pathways." (PMID 21738467, 2011). "In addition, there was a tendency for the Indo-Oceanic ZERO spoligotype to induce less TNF-α and IL-1β than the EA14_VNM spoligotype after 24 and 48 hours of infection, although these differences did not achieve statistical significance (p>0.05)." (PMID 21931620, 2011). "Furthermore, it increased the relative and absolute numbers of LCMV-specific CD4+ T cells producing TNFα on day 11, but not on day 8 after infection." (PMID 21966366, 2011).
infection (continued). "In contrast, infection with the capsule-deficient mutant strain 10 Δcps did not cause an increased PMN migration rate; in fact this was significant lower than in S. suis strain 10 or TNFα-treated cells, and comparable to that of control cells." (PMID 21592385, 2011). "In response to infection (LCL-Vacc), all cytokines, with exception of IFN-γ, were detected in all clones and, similarly to the response to low antigen concentration (peptide at 5 ng/ml), GM-CSF, TNF-α, IL-13 and IL4 were detected at 48 hours at significantly higher levels than those at 6 hours." (PMID 21931646, 2011). "Thus, use of a PDE4i has enabled us to achieve this critical balance between limiting the negative effects of TNF-α, while retaining sufficient immunity to control infection." (PMID 21364878, 2011). "We showed that innate TNF-α responses and TNF-α: IL-10 ratios upon TLR2 stimulation of PBMCs were significantly higher in S. haematobium-infected children compared with those without infection, in the face of enhanced regulatory adaptive responses to schistosomal antigens." (PMID 21931706, 2011). "In order to evaluate whether PbAOX suppression could alter the cytokine profile in alveolar macrophages, we determined the gene expression of IL6, IL10, IL12p40, and TNF-α during infection of non-activated and IFN-g-activated alveolar macrophages." (PMID 22039556, 2011). "In contrast, HEK293-TLR2 and HEK293-TLR5 cells were highly competent for inducing the secretion of IL-8 and TNF-α cytokines in a cagPAI-independent manner, suggesting that the expression of TLR-2 or TLR-5 has profoundly changed the capability to trigger pro-inflammatory signalling upon infection." (PMID 21573018, 2011). "Hence, it is possible that all the TNF-α reserves are exhausted in 16 h post-infection, and no fresh TNF-α is synthesized and released from monocytes in response to shear stress." (PMID 21249123, 2011). "A recent Italian registry study reported an incidence rate of 3.59 serious infections per 100 patient-years (95% CI 2.77-4.41) in the first 36 months of anti-TNF therapy, without significant differences in incidence and type of infection between the different anti-TNF agents." (PMID 22081766, 2011). "Alternatively, hyperplasia in the TNF KO ME could reflect low-grade infection with endogenous microorganisms in the absence of this critical cytokine." (PMID 21269505, 2011). "However, although Tm-TNF confers early protection against recrudescence M. tuberculosis, Tm-TNF alone does not sustain long term control of the infection, indicating that solTNF is needed for controlling chronic infection." (PMID 22132068, 2011). "Importantly, rates of serious infection did not increase with prolonged use of tocilizumab, and serious infections occurred at rates similar to those reported for RA patients treated with TNF inhibitors or other biologic agents." (PMID 21884601, 2011). "Contrary to BCG, on extending the time of evaluation to 16 weeks post-infection, rBCG vaccination resulted in a considerable decline in the levels of IFNγ and IL10; a significant increment in the levels of IL12 (p<0.05), while the levels of TNFα and TGFβ remained unaltered." (PMID 21533158, 2011). "Indeed, HeLa cells infections with a tir mutant confirmed Tir's non-essential role in inhibiting TNFα-induced IL8 secretion but also revealed a small, but statistically significant defect." (PMID 22144899, 2011). "These included chemokine ligand IP-10 and genes controlled by pro-inflammatory cytokines TNF-α, IL-1β, IFN-γ; namely, interferon regulatory factor 1, Cd274 antigen, metallothionein 2, proteasome subunit (Psmb9), and tumor necrosis factor Tnfsf10 were progressively up-regulated after infection." (PMID 20082697, 2010).
infection (continued). "Second, the higher susceptibility of Myd88−/− mice could be directly attributed to the defective activation of CD4+ T cells demonstrated here, as this cell population has also been demonstrated to be essential for resistance to infection, probably through IFN-γ and TNF-α secretion." (PMID 20442858, 2010). "In this regard, although IFN-γ and MyD88 signaling were documented to contribute to TNF and NO production in T. brucei infected mice, it is unknown whether IFN-γ and/or MyD88 signaling are involved in Tip-DC differentiation during infection." (PMID 20714353, 2010). "The low number of cases (including only two diabetic cases) in this study did not permit to confirm this hypothesis concerning TJA infections in case of TNFα-blocker therapy." (PMID 20637100, 2010). "Both IFN-γ and TNF-α can be produced after T. cruzi-induced triggering of the innate immune response (mainly by NK/NKT cells and macrophages/DC respectively), as well as by CD8+ and CD4+ T lymphocytes later in the infection course, as part of the acquired response to the parasite." (PMID 20442858, 2010). "P. berghei ANKA (PbA) infection of C57BL/6 mice, which is the best available model of CM, is characterized by the development of strong pro-inflammatory immune responses, including macrophage activation and the production of TNF, IL-12, IL-1β, IL-6, ROI and NO." (PMID 20126448, 2010). "Law suggested that SARS-CoV, during infection of dendritic cells, evades the immune response by down-regulating expression of the anti-viral chemokines IFN-α, β and γ and IL-12p40, while simultaneously up-regulating that of others: for example, TNF-α, IL-6, MIP-1α, and IP-10." (PMID 20478047, 2010). "Monofunctional IL-2 or TNF-α producing HIV-specific CD8+ T cells were very infrequent in this cohort of chronically infected patients and only a small proportion of HIV-specific CD8+ T cells expressed TNF-α responses confirming previous studies that this effector function is lost early in infection." (PMID 20638093, 2010). "Micro-beads array analyses indicate that Leishmania infantum amastigotes infection induces a higher secretion of several cytokines in these cells, and use of specific neutralizing antibodies revealed that the Leishmania-induced increase in HIV-1 replication is due to IL-6 and TNF-α." (PMID 19468304, 2009). "However, significant reduction in the production of TNF, IFNγ, and IL10 were observed in SR-B1−/− mice following infection with a high dose of Mtb (1000 CFU/mouse), which marginally affected the size of inflammatory foci but did not influence bacterial burdens." (PMID 20041149, 2009). "For the Pietrain pigs a negative correlation between the TNF-α production by blood leukocytes in vitro and clinical scores was found at pre-infection as well as at 4 and 21 days post-infection (r = -0.45; p < 0.05 at day -7; r = -0.48; p < 0.05 at day 4 and r = -0.61; p < 0.05 at day 21)." (PMID 19383119, 2009). "LPS treatment of uninfected THP-1 cells also co-induced the secretion of IL-1β and TNF to comparable levels (data not shown), suggesting that infection with vMyxM013-KO virus was as comparably robust at inducing these two cytokines as the triggering of TLR4 activation with LPS." (PMID 19851467, 2009). "A rabbit Wiffle ball infection model assessed GML and DDG (1 mg/ml instilled into the Wiffle ball every other day) effects on S. aureus (MN8) growth (inoculum 3×108 CFU/ml), toxic shock syndrome toxin-1 (TSST-1) production, tumor necrosis factor-α (TNF-α) concentrations and mortality over 7 days." (PMID 19838303, 2009). "In the present study, we report that infection of human THP-1 monocytic cells with the vMyxM013-KO virus, unlike the parental MYXV, unexpectedly induced rapid and dramatic secretion of diverse pro-inflammatory cytokines such as TNF, IL-6 and MCP-1, all of which are regulated by NF-κB." (PMID 19851467, 2009).
infection (continued). "We did not assess other markers (for example, IL-6, IL-8, TNF-α, endotoxin, serum amyloid A, or neopterin) that could be considered to augment the diagnosis of infection in neutropenic patients, as explored by others." (PMID 19291300, 2009). "Moreover, this alteration was neither observed when infection was performed using PorB-deficient mutants (NM0401 and NM0705) nor upon TNF-α treatment." (PMID 19412525, 2009). "PRRs detect pathogen-associated molecular patterns (PAMPs) and signal the presence of infection to the host, activating host defense, including antiviral (IFN-α/β) and pro-inflammatory cytokine (interleukin-1β (IL-1β), IL-6, IL-18 and tumor necrosis factor α (TNF-α) production." (PMID 21994567, 2009). "Further, infection alters TLR responsiveness, as IL-12 production (as measured by ex vivo intracellular staining of CD11c+ DCs) in response to LPS stimulation is reduced, while IL-6, TNF-α and in particular, IL-10 all increase following infection with either nematode parasite." (PMID 19766674, 2009). "The high level of IFN-γ and IL-12 at 4 weeks, and RANTES at 8 weeks post-infection in TNFtm/tm mice suggest a strong Th1 response, which was confirmed by an enhanced cutaneous delayed-type reaction in infection in both TNFtm/tm and TNF−/− mice (data not shown)." (PMID 18544042, 2008). "In addition, TNF production by monocytes/macrophages was not different between treatment groups at these times after infection, and no TNF was detected in DC (data not shown)." (PMID 18463695, 2008). "Here we demonstrated that the Δ1-12 TNF mutant, which expresses only membrane TNF is partially resistant to infection to the non-virulent vaccine strain M. bovis BCG with 50% of mice surviving the experimental period, while all TNF-deficient mice succumb to infection." (PMID 18544042, 2008). "Notably the expression levels of other major pro-inflammatory mediators such as TNFα and IL-1 were not affected by B. anthracis Sterne or ΔpXO1 infection." (PMID 18698416, 2008). "However, despite iNKT cell IFNγ and TNF production, and enhanced NK cell IFNγ production in the liver following α-GalCer administration during infection, the control of L. donovani was not improved." (PMID 18463695, 2008). "This may explain why a higher percentage of tmTNF has a negative impact on infection containment during anti-TNF antibody treatment: with more tmTNF, more MAs and T8 cells are lost from the granuloma." (PMID 17953477, 2007). "This particular Sp1 site is involved in regulation of the human TNF gene in cells of the monocyte/macrophage lineage in response to MTb infection and to treatment with LPS but has no apparent role in TNF gene regulation in T cells activated by calcium influx or by T cell receptor ligands." (PMID 17637837, 2007). "Therefore, bone marrow derived cells expressing membrane TNF, but not lymphocytes, are sufficient to control infection in reconstituted TNF-KO mice." (PMID 16285886, 2005). "Furthermore, the concurrent elevation of TNF-α suggests an altered and potentially dysregulated inflammatory pathology, which may contribute to tissue damage without effectively containing the infection." (PMID 41313186, 2026). "Especially in the case of the proinflammatory cytosine TNF-α, there seems to be a close correlation with infections with atypical pathogens and a marked immune response, as well as with increased IL-1β and IL-6 values compared with the absence of infection (both in the presence and absence of PCOS)." (PMID 40647668, 2025).